TNF (tumor necrosis factor)
Diseases named in the same sentence as TNF in open-access papers (continued):
Sharing a sentence is not in itself a finding about the gene and the disease.
tumor (continued). "Upon flagellin treatment, flagellin reduced tumor growth along with an increase in the concentration of TNF-α, and higher mRNA levels of Tnfa, whereas the mRNA levels of Arg1 were reduced." (PMID 38331868, 2024). "But on the other hand, it also stimulates the proliferation, survival, migration and angiogenesis of some cancer cells that are resistant to TNF-induced cytotoxicity, leading to the development of tumor." (PMID 38594751, 2024). "In the passive pathway, bacteria get trapped in the disordered tumor vasculature and migrate within the tumor due to inflammation from a rapid surge in TNF-α." (PMID 39594765, 2024). "As pro-inflammatory cytokines, IFNγ and TNF-α promote other immune cell activation and can induce tumor cell apoptosis." (PMID 39179536, 2024). "CTCL recognition of this Ag induces its activation and leads to the secretion of cytokines, including tumor necrosis factor α (TNF‐α), perforin, and granzyme B, which work together to kill target tumor cells." (PMID 38525112, 2024). "Notable, IL-15, IL-18, IL-1β, and TNFα in the host serum, potentially derived from the tumor microenvironment through various pathways, promoted sustained angiogenesis involving endothelial cells." (PMID 39451257, 2024). "Mechanistically, bacterial colonisation upregulates tumour TNF-α expression, which acts as an attractant for neutrophils." (PMID 39272829, 2024). "Evaluation of the type and nature of the response of tumor cell lines of different genesis to different doses of cytokine showed that the cellular response to TNF depended on the expression density of TNFR1 and TNRF2 as well as on their co-expression on cells." (PMID 38651368, 2024). "M1 macrophages, activated by IFN-γ, lipopolysaccharides, and TNF-α, play a role in fostering inflammatory responses against tumor cells." (PMID 38293522, 2024). "CD8+ cytotoxic T lymphocytes (CTLs) are the primary tumor-killing cells, which can activate themselves through T cell receptor binding to antigens presented by MHC-I molecules, expressing high levels of IFNγ, TNFα, perforin, and granzymes to kill tumor cells." (PMID 38523155, 2024). "Through the regulation of immune responses and reinforcement of antitumor effects, these interventions influence the levels of Th1, Th17, and Th2 cytokines, augmenting IL-2, tumor TNF-α, IFN-γ, and IL-17A, while diminishing IL-10 levels." (PMID 38794206, 2024). "iNK-CTLs can exert cytotoxicity through the Fas/FasL pathway, the TNF-α pathway, and the granzyme and perforin pathways of tumor cells carrying CD1d molecules." (PMID 38515134, 2024). "We therefore subsequently discuss our findings with a focus on IL‐17A, its synergism with TNF and the promotion of tumor cell adhesion to the mesothelium." (PMID 38566518, 2024). "Transcriptomic profile changes in cancer cells co-cultured with bacteria revealed significant alterations in several tumor and inflammation-related signaling pathways, including the TNF, IL-17, and NF-kappa B signaling pathways and Th17 cell differentiation." (PMID 39850896, 2024). "Several reports have revealed that lymphocytes can activate a cell-mediated immune response and stimulate the release of cytokines such as interferon and TNF-α to exert organismal protective effects, even leading to the lysis of tumor cells." (PMID 38501103, 2024). "The innate immune response was further amplified by the increase in the levels of pro-inflammatory factors, such as IL-6 in serum and TNF-α in tumor tissues." (PMID 39010088, 2024). "Alternatively, VHHs conjugated with proteins (e.g., cucurmosin, pseudomonas exotoxin), cytokines (e.g., IFNγ, IL-2, TNFα) or peptides show promising potential of inhibiting tumor growth." (PMID 38254860, 2024). "Previous studies have shown that the N1 markers TNFα, IL12, and CXCL10 are not only associated with neutrophils’ anti-tumor activity but also linked to ER stress signaling." (PMID 39261943, 2024).
tumor (continued). "Treatment with ipilimumab stimulated ADCC and TNF-α secretion by NK cells in vitro and resulted in tumor inhibition in a chimeric murine xenograft model." (PMID 39339180, 2024). "As is well known, IL-6 can mediate inflammatory responses, whereas TNF-α is central to coordinating inflammatory immune responses, reflecting direct changes in the tumor microenvironment." (PMID 39065602, 2024). "M1 macrophages produce pro-inflammatory cytokines (e.g., tumor necrosis factor-α and IL-6) and induce anti-tumor immune responses." (PMID 39684424, 2024). "Anti-tumor immune pathways such as IL-18 signaling pathway and TNF signaling pathway indicate its activated state of immune engagement." (PMID 39232806, 2024). "M1 macrophages can enhance the ability of CD8 + T cells and NK cells to emit tumor cells or induce tumor cell apoptosis by secreting TNF, IL-6, IL-12, and other cytokines." (PMID 38713256, 2024). "CAR-T cells also release cytokines, such as interferon-gamma (IFN-γ) and tumor necrosis factor-alpha (TNF-α), which subsequently activate the host immune system to inhibit tumor growth and metastasis." (PMID 38146589, 2024). "TNF-α can be secreted by tumor cells and host cells in the tumor microenvironment to enhance the oncogenic process." (PMID 38734702, 2024). "AuNPs controlled the TNF-cytokine expression and improved the proinflammatory response in tumor-bearing mice." (PMID 40808797, 2024). "The increase of the M1 phenotype prior to and during the pathology of MS and the enrichment of the CSF with inflammatory cytokines, such as IL-1β and tumor TNF-α, lead to the rapid activation and proliferation of CD4+ T cells." (PMID 39000461, 2024). "Studies revealed that, although TNFα inhibit cell proliferation, tumor cells as in a B16 murine melanoma model, secrete low levels of this cytokine promoting infiltrating myeloid cells recruitment, vascularization and progression of the cancer." (PMID 39015505, 2024). "NF-kB activation triggers secretion of various factors such as IL-6, IL-12, IL-17, IL-18, and tumor necrosis factor-alpha (TNF-alpha), causing sustained inflammation within tumor microenvironment." (PMID 39639864, 2024). "The numbers of TILs per gram tumor secreting GzmB, IFNγ, TNFα, and IL-2 were considerably higher in both primary and secondary tumor in the hRT/lena treatment group." (PMID 38646638, 2024). "NK cells are also an important source of cytokines in vivo, which can induce tumor eradication by secreting distinct cytokines (such as TNF-α, IFN-γ, IL-2, etc.)." (PMID 39065636, 2024). "We showed that fibroblasts activated through tumor-bearing derived EVs showed upregulated expression levels of multiple inflammatory cytokines, such as IL-1β, IL-6, IL-8, TNF-α, and TGF-β, in a time-dependent manner." (PMID 39056778, 2024). "TNF-α displays pro-tumor activity by stimulating the growth, proliferation, invasion, angiogenesis, and metastasis of cancer cells by activating nuclear factor kB (NF-kB), an important cell survival signal that inhibits the apoptotic process." (PMID 39408920, 2024). "For the TNF signaling pathway, 15/23 transcripts were confirmed to be individually de-regulated when comparing the expression in tumor-rich versus tumor-sparse regions." (PMID 39001353, 2024). "As one of the pro-inflammatory cytokines, tumor necrosis factor-α (TNF-α) is generally associated with killing and inhibiting the activity of tumor cells." (PMID 38651009, 2024). "In vitro and in vivo experiments validated that CXCR1+ neutrophils resulted in resistance to third-generation EGFR-TKI via activating TNF-α/NF-κB signaling pathway in tumor cells." (PMID 39638994, 2024). "Further studies showed that PLOD3 facilitated the T cell activation in the tumor microenvironment and affected the TNF-α/ NF-κB pathway." (PMID 38184566, 2024).
tumor (continued). "The authors examined that EGFR806-CAR-T cells with short spacers in the extracellular domain induced the strongest production of effector cytokines IL-2, IFN-γ and TNF-α after tumor recognition." (PMID 38339374, 2024). "M0 TAMS are usually dormant, while the proinflammatory M1 TAMs mainly produce cytokines such as tumor necrosis factor-α (TNF-α) and interleukin-1 (IL-1), which inhibit and kill tumor cells." (PMID 38595813, 2024). "It is possible that other factors such as the expression of cytokines IFN-γ or TNF-α are also involved in the process of inducing apoptosis of tumor cells." (PMID 39845973, 2024). "Tumor Necrosis Factor-Alpha (TNF-α): TNF-α is a pro-inflammatory cytokine that can have both pro- and anti-tumor effects." (PMID 38397971, 2024). "While in untreated mice the frequency of cytokine-producing and, in particular, of multifunctional CD8 T cells were very low, KV vaccination significantly increased the proportion of IFN-γ+TNF-α+CD107α+ triple positive CD8 T cells within the tumor." (PMID 38893156, 2024). "Cytokines secreted by T cells were assayed, including TNF-α, IL-10, and IL-4, associated with generating antitumor CTL responses and tumor immune surveillance." (PMID 39772073, 2024). "In GBM-NS models with low CSPG4 expression, microglial cells surrounding the tumor induced CSPG4 upregulation on the tumor cell surface by releasing TNF-α, thereby enhancing the therapeutic efficacy of CAR-T cells." (PMID 39506843, 2024). "TAM secretes vascular endothelial growth factor (VEGF), TGF-β, and IL-10, and low levels of TNF-α, IL-12, and IL-1β to induce tumor blood vessel growth and angiogenesis." (PMID 39000385, 2024). "The IAP inhibitor birinapant makes tumor cells more sensitive to CL-derived TNF killing, while TNF is elevated after PD-1 blockade, and the combination of the two further enhances the efficacy of anti-PD-1 antibody therapy." (PMID 39253578, 2024). "There have been mixed pre-clinical and retrospective data as to the potential impact of TNF blockade on tumor outcomes." (PMID 39737191, 2024). "We found that the levels of inflammatory cytokines, such as IFNγ and TNFα, were increased in tumor-bearing mice." (PMID 38690266, 2024). "Macrophage TNF-α-driven tumor cell pyroptotic death requires nuclear PD-L1, caspase-8, and GSDMC in vivo." (PMID 39300122, 2024). "Both sTNF-R1 and sTNF-R2 are found in the vascular circulation and modulate the activity of TNF-α in a physiological manner, but sTNF-Rs are often elevated in the serum/plasma of tumor patients." (PMID 38339276, 2024). "On the other hand, TNF-α promotes tumor development by upregulating the nitric oxide-dependent pathway and inhibiting DNA repair." (PMID 38444674, 2024). "Blocking TNF-α by a monoclonal antibody effectively inhibits tumor growth, increases tumor immunity, and decreases the member of CAMs-M2 in murine CRC cells-transplanted mouse model." (PMID 39125923, 2024). "Enzyme‐linked immunosorbent assays demonstrated that the AISI‐pLuxI‐htrA strain effectively increased the key antitumor cytokines level, including IFNγ and TNFα, within the tumor and peripheral blood compared to those in the AISI‐NC strain." (PMID 39058336, 2024). "This binding causes lymphocytes to release cytokines IL-2, IL-1b, IL-6, TNF and Ifny into the medium, which leads to the appearance of cytotoxic lymphocytes in PBMC capable of lysing HLA-negative tumor cells." (PMID 38203798, 2024). "On one hand, the inhibition of the PI3K/Akt signaling pathway can suppress proto-oncogenes and reduce the expression of Src Family Kinases and TNF genes, thereby inhibiting tumor cell proliferation and migration and promoting apoptosis." (PMID 39274982, 2024). "Various stimulatory factors released by tumor cells, such as TNF-α, IL-1β, etc., can activate the NF-κB signaling pathway, thus promoting the expression of CCL2." (PMID 39065562, 2024). "It is known that tumor tissues are infiltrated with T cells, monocytes, and other cells producing TNF." (PMID 38338920, 2024).
tumor (continued). "More importantly, tumor‐localized inflammation is concurrently reduced, as evidenced by decreased levels of pro‐inflammatory factors, including TNF‐α and IL‐6, in tumor tissues at the end of the therapeutic period." (PMID 38943265, 2024). "The interaction between TIM3 and galectin 9 (Gal9) in CD8+ T cells leads to the reduction of the production of cytokines (IFNγ, IL-2, and TNFα), the inhibition of T cell proliferation, and the inhibition of anti-tumor immunity." (PMID 39372416, 2024). "Nanoparticle-loaded TLR3 stimulators have been shown to have inhibitory effects on tumor development by producing high levels of TNF-α and nitric oxide (NO)." (PMID 39169402, 2024). "Pro-inflammatory TAMs express TH1 response-inducing cytokines such as IL1α, IL1β, IL12 and TNFα while pro-tumor TAMs express IL10, CCL8, and CCL22 that are tumor promoting." (PMID 38802355, 2024). "Probiotic strains and bacterial CFSs that promote generalized mucosal immune responses via proinflammatory cytokine production (e.g., TNF-α, IL-1β and IL-6) were found to fortify the host defense system and provide anti-pathogen and anti-tumor effects." (PMID 39534506, 2024). "Still, a balance between high and low concentrations of IL-17 and TNF-α can exert opposing effects on tumor growth in various models, warranting further investigation." (PMID 39650654, 2024). "Macrophage or DC was selected as a tool to targeted deliver TNF to cancers because they are abundant support cells in the tumor microenvironment and are terminal differentiated cells and their life span can be weeks to months." (PMID 39105847, 2024). "The tumor treated with P-E/S Lip expressed higher protein levels of TNF-α and IL-6 compared with the control tumors." (PMID 39068444, 2024). "Flow cytometric analyses demonstrate significantly increased numbers of tumor-killing CD3+ CD8+ CTL in the spleen and in the contralateral distant tumor, as well as systemically increased cytokine levels of TNF-α, INFγ and IL-10 in the serum measured by ELISA." (PMID 39599834, 2024). "Among the TNFs, the Tumor Necrosis Factor Alpha-induced proteins (TNFAIPs) derived from the TNF are involved in cell proliferation, invasion, and metastasis of tumor cells." (PMID 39765744, 2024). "CD8+ T cells are cytotoxic lymphocytes that can directly eradicate tumor cells and generate proinflammatory cytokines, including IFN-γ and tumor TNF-α." (PMID 39324018, 2024). "M1 macrophages produce reactive nitrogen species, reactive oxygen species, and pro-inflammatory cytokines such as IL-6 and TNF-α to inhibit tumor growth." (PMID 38191571, 2024). "The results showed that the proportion of immunosuppressive T cells (TIM3+ T cells) was significantly increased and the tumor-killing factor TNFα secreted by T cells was significantly reduced, showing a state of T-cell exhaustion." (PMID 39399179, 2024). "The presence of E. coli, specifically EcN and K-12, in the tumour transition zone also reportedly led to increased necrosis, possibly as a result of upregulation of TNF-α leading to tumour cell apoptosis and decreased blood vessels within the region." (PMID 39272829, 2024). "TILs enhance anti-tumor immune responses by producing various cytokines, such as interferon-γ and tumor necrosis factor-α." (PMID 39555450, 2024). "According to the results of the current study, FIGN has a preliminary role in pro-tumor immunity, including natural killer cell-mediated cytotoxicity, TNF signaling, NF-kappa B signaling, Toll-like receptor signaling, and JAK-STAT signaling." (PMID 38421251, 2024). "Meanwhile, IFN-γ or TNF-α from TAMs upregulate the PD-L1 expression of tumor cells, and IL-10 and TGF-β from TAMs influence the B7-H1 expression of tumor cells." (PMID 38672714, 2024).
tumor (continued). "There is already evidence that tumor necrosis factor-α (TNF-α) plus interferon-γ (IFN-γ) was effective against a wide range of tumor cell types, highlighting its potential for clinical application." (PMID 38553639, 2024). "This is further supported by enrichment analysis showing a propensity for tumor invasion and metastasis in high-risk individuals, linked to the deregulation of JAK-STAT and TNF pathways." (PMID 38594466, 2024). "SCFAs (butyrate and valerate), fiber, or SCFA-producing bacteria supplements increase the intratumoral T cells, INF-γ, and TNF-α and result in the inhibition of tumor growth and improvement of anti-tumor immune response." (PMID 39022585, 2024). "Tumor necrosis factor alpha (TNF-α) is an important defense cytokine produced by macrophages against tumor cells." (PMID 38998999, 2024). "Astragalus polysaccharides can partly promote the secretion of IFN‐γ and TNF‐α by intestinal mucosal γδT cells, and inhibit the growth of tumors in tumor‐bearing mice." (PMID 38604998, 2024). "MSCs can be stimulated within the tumour niche by pro-inflammatory cytokines such as TNF-α, IFN-γ or IL-1β, which are produced by both macrophages and tumour cells." (PMID 39120301, 2024). "In GC, M1 secrete CXCL9 and CXCL10, IL-1β, TNF-α, and IL-8, among others, stimulating tumor growth, while M2 secrete anti-inflammatory cytokines such as IL-33, IL-10, and TGF-β." (PMID 38455038, 2024). "Classically activated macrophages (M1) exert anti-tumoral activities by secreting IL-1β, IL-12 and TNF-α, while alternatively activated macrophages (M2) fuel tumor growth through immune suppression and promotion of angiogenesis and metastasis." (PMID 39335188, 2024). "Upon co-incubation with CD19-expressing tumor cells, the activation of NFκB and NFAT, the upregulation of CD69, CD25 and 4-1BB, and the secretion of IFNγ and TNF were severely impaired by the phospho-mimicking CAR variants compared to the WT CAR." (PMID 38779683, 2024). "Chronic alcohol consumption can result in the recruitment of monocytes and macrophages into the tumor microenvironment, resulting in the production of pro-inflammatory cytokines, such as tumor necrosis factor (TNF-α) and the interleukins IL-1, IL-6, and IL-8." (PMID 39727994, 2024). "This polarization results in increased secretion of IL-6, IL-8, and TNF-α, impacting tumor resistance, growth, angiogenesis, and other facets of tumor progression." (PMID 39578849, 2024). "A flow chamber system including TNF-α stimulated HUVEC was used to evaluate the ability of targeted MB binding in a dynamic environment alike the tumor microvasculature." (PMID 39218888, 2024). "For example, Th1 CD4+ cells secrete pro-inflammatory mediators INF-γ and TNF-α, and trigger the anti-tumor activity of NKs, thus activating a powerful anti-cancer immune response." (PMID 39050852, 2024). "HMGB1 binds to advanced glycosylation end product‐specific receptor (AGER) to release TNF‐α synergistically for anti‐tumour immunotherapy." (PMID 38652105, 2024). "Analysis of T-cell profiles from CD83OE tumor mice in vivo revealed an increase in IL-2 expression and the largest proportion of TNFα-producing cells." (PMID 39601621, 2024). "Th17 cells can suppress tumor growth and metastasis and promote cancer cell apoptosis by secreting TNF-α, the soluble dimer cytokine interferon (IFN)-γ, IL-17, IL-21, and IL-22." (PMID 39534095, 2024). "The authors also described aggravation of inflammatory reaction by macrophage and neutrophil infiltrates and tumor-related IL-6 and TNF-α cytokines." (PMID 40135141, 2024). "Pentacyclic triterpenoids modulate inflammatory pathways by downregulating pro-inflammatory cytokines, such as IL-6 and TNF-α, thereby mitigating the chronic inflammation that drives tumor progression." (PMID 39861671, 2024). "Recently, the interaction between TNFR2 of the tumor cell and the TNF-α bound to the monocyte membrane was reported, triggering tumorigenic inflammation in NB." (PMID 39408920, 2024).